RNU4-9P (RNA, U4 small nuclear 9, pseudogene)
Gene: Small nuclear RNA gene on chromosome 13 (21,038,529 to 21,038,667, reverse strand). Ensembl gene ENSG00000201821.
Homologues: Orthologues: chimpanzee U4 (99% identical), macaque U4 (94% identical), rabbit U4 (58% identical). Paralogues in human: RNU4-31P (78% identical), RNU4-78P (75% identical), RNU4-41P (71% identical), RNU4-65P (65% identical), RNU4-79P (62% identical), RNU4-28P (58% identical), RNU4-39P (58% identical), RNU4-52P (57% identical), RNU4-67P (57% identical), RNU4-68P (56% identical), RNU4-13P (55% identical), RNU4-36P (55% identical), and 81 more.